HINT1 (histidine triad nucleotide binding protein 1)
Diseases named in the same sentence as HINT1 in open-access papers (continued):
Sharing a sentence is not in itself a finding about the gene and the disease.
nicotine dependence (4 papers, 2015 to 2024). Physical and psychological dependence on nicotine. "A study of the relationship between mutations in the HINT1 gene and nicotine dependence found that smoking is associated with increased HINT1 gene expression." (PMID 39062900, 2024). "Association analysis from two independent samples indicates that mutations in the HINT1 gene are associated with phenotypes of nicotine dependence." (PMID 29214080, 2017). "The authors concluded that variants of the HINT1 gene are associated with pathomechanisms of nicotine dependence, as a change in mRNA expression in smokers may suggest that the polymorphism has some biological relevance in the development of ND." (PMID 38279213, 2024). "In a study by Jackson (2011) on analysing the three HINT1 polymorphic sites that we describe, they found significant associations between rs2526303 and rs3864283 with nicotine dependence, the number of cigarettes smoked daily, and the Fagerström Test of nicotine dependence score." (PMID 39062900, 2024).
bipolar disorder (3 papers, 2009 to 2024). A disorder of the brain that causes unusual shifts in mood, energy, activity levels and the ability to carry out day-to-day tasks. "Moreover these data are in consistent with microarray results demonstrating a decrease in PKCI/HINT1 expression in the brains of bipolar disorder patients, making it a candidate molecule for the disease." (PMID 19912621, 2009). "Originally PKCI/HINT1 isolated from bovine brain extracts was identified as an in vitro inhibitor of PKC isoforms and PKC inhibitors are promising targets for bipolar disorder drug development." (PMID 19912621, 2009).
gastric cancer (3 papers, 2020 to 2023). A primary or metastatic malignant neoplasm involving the stomach. "Research has shown that reduced levels of HINT1 in liver and gastric cancer may be linked to the hyper-methylation of the Hint1 promoter region." (PMID 38068718, 2023). "The decreased Hint1 mRNA levels in FHGC patient samples could be a predisposing marker to develop gastric cancer." (PMID 33671384, 2021). "Hint1 gene and mRNA expression were assessed in a family history of gastric cancer (FHGC) cases." (PMID 33671384, 2021). "In the gastric cancer cell line SGC-7901, Hint1 inhibits cell proliferation, arrests the cell cycle in G1 phase, and reduces the DNA damage repair induced by radiation, increasing the radiosensitivity." (PMID 33671384, 2021).
mood disorder (3 papers, 2017 to 2024). A cognitive disorder a disturbance in which the person's mood is hypothesized to be the main underlying feature. "In encephalic regions closely associated with mood disorders, namely the PFC, NAc and Hip, altered duration of lighting led to upregulated HINT1, accompanied by increased BAX and decreased BCL-2." (PMID 29937721, 2018). "Furthermore, HINT1 was upregulated in four encephalic regions, indicating that HINT1 may be involved in mood disorders and cognitive impairments due to altered light exposure." (PMID 29937721, 2018). "Based on the potential links between histidine triad nucleotide binding protein 1 (HINT1) and mood disorders, we also examined the expression of HINT1 and related apoptosis factors in the suprachiasmatic nucleus (SCN), prefrontal cortex (PFC), nucleus accumbens (NAc) and hippocampus (Hip)." (PMID 29937721, 2018).
embryonal carcinoma (2 papers, 2021 to 2025). A non-seminomatous malignant germ cell tumor characterized by the presence of large germ cells with abundant cytoplasm resembling epithelial cells, geographic necrosis, high mitotic activity, and pseudoglandular and pseudopapillary structures formation. "To determine whether HINT1 negatively regulates Tfam expression, we knocked down (KD) HINT1 in mouse embryonal carcinoma P19.CL6 cells and observed upregulated Tfam expression." (PMID 39909188, 2025). "To further validate Caren/Hint1 mRNA interaction, we performed RNA antisense purification (RAP) analysis using mouse embryonal carcinoma P19.CL6 cells crosslinked with disuccinimidyl glutarate (DSG) and formaldehyde (FA)." (PMID 33953175, 2021).
liver cancer (2 papers, 2021 to 2023). An epithelial or non-epithelial malignant neoplasm that arises from the liver. "An increase in Hint1 expression by Taraxasterol inhibits the growth of liver cancer cells and regulates Bax, Bcl2, and cyclin D1 expression in human liver cancer." (PMID 33671384, 2021). "HINT1 has recently been identified as a tumor suppressor that effectively hinders the development of various cancers in mice, including ovarian, gastric, breast, and liver cancers." (PMID 38068718, 2023).
Stroke (2 papers, 2017 to 2021). Sudden impairment of blood flow to a part of the brain due to occlusion or rupture of an artery to the brain. "In the same model, cannabidiol reduced NMDA-mediated seizures and provided neuroprotection after stroke while promoting morphine antinociception by disrupting the regulatory association of Sigma1R with the histidine triad nucleotide binding protein 1 (HINT1) and the NR1 subunit of NMDARs." (PMID 34445144, 2021). "Previous exposure of mice to the FST brought about increases in stroke-induced neural damage in HINT1−/− mice but did not augment its severity in HINT1+/+ WT mice." (PMID 28240305, 2017). "We could observe that PKC inhibition prior to surgery did not affect stroke-induced neurological damage severity in HINT1+/+ WT mice; however, this intervention greatly enhanced stroke-induced brain damage in HINT1−/− mice." (PMID 28240305, 2017).
amyotrophic lateral sclerosis (1 paper, 2021). Amyotrophic lateral sclerosis (ALS) is a neurodegenerative disease characterized by progressive muscular paralysis reflecting degeneration of motor neurons in the primary motor cortex, corticospinal tracts, brainstem and spinal cord. "Thus, HINT1 mutants may promote α2δ1 and σ1R mediated activation of NMDARs, and accordingly, amyotrophic lateral sclerosis could be treated with drugs reducing NMDAR activity." (PMID 34827679, 2021).
anxiety disorder (1 paper, 2024). A category of psychiatric disorders which are characterized by anxious feelings or fear often accompanied by physical symptoms associated with anxiety. "A potential role for HINT1 in MDD and anxiety disorders was recently described." (PMID 38279213, 2024).
aortic aneurysm (1 paper, 2025). A ruptured aneurysm located in the wall of the proximal portion of the descending aorta proceeding from the arch of the aorta. "Increased HINT1 expression in the vascular smooth muscle is associated with the occurrence of aortic aneurysm." (PMID 40198125, 2025). "The protein and mRNA levels of HINT1 were markedly higher in aorta samples from aortic aneurysm patients than those in normal aorta samples from donors." (PMID 40198125, 2025). "Taken together, these results suggest that HINT1 in VSMC aggravates aortic aneurysm by increasing the expression of ITGA6." (PMID 40198125, 2025). "Knockout of Hint1 in VSMCs alleviated aortic aneurysm, and simultaneous overexpression of Itga6 reversed this protective effect." (PMID 40198125, 2025). "HINT1 was upregulated both in aortic tissue from patients with aortic aneurysm and angiotensin II–induced aortic aneurysm mice." (PMID 40198125, 2025). "Here, we revealed the role of histidine triad nucleotide-binding protein 1 (HINT1) in aortic aneurysm." (PMID 40198125, 2025). "VSMC-specific HINT1 deletion alleviated aortic aneurysm via preventing VSMC phenotypic switching." (PMID 40198125, 2025). "Impact of HINT1 on aortic aneurysm relies on its regulation of ITGA6." (PMID 40198125, 2025). "Taken together, upregulation of HINT1 expression in VSMCs is correlated with aortic aneurysm in both humans and mice, suggesting that HINT1 may play an important role in the progression of aortic aneurysm." (PMID 40198125, 2025). "Next, we clarified the role of HINT1 in the aortic aneurysm." (PMID 40198125, 2025). "Moreover, immunofluorescence staining also revealed increased HINT1 in aorta samples from aortic aneurysm patients than that from control subjects." (PMID 40198125, 2025). "VSMC-specific knockout of Hint1 alleviates Ang II–induced aortic aneurysms in vivo." (PMID 40198125, 2025). "Thus, the HINT1/ITGA6/FAK axis emerges as a potential therapeutic strategy in aortic aneurysm." (PMID 40198125, 2025). "In this study, by using animal and cell models, we found that HINT1 in VSMCs promoted VSMC phenotypic switching and aggravated aortic aneurysm induced by angiotensin II (Ang II) in mice." (PMID 40198125, 2025). "Taken together, these findings demonstrated that HINT1 promotes VSMC phenotypic switching and aggravates aortic aneurysm in an ITGA6-dependent manner through direct interaction with TFAP2A, which is responsible for the transcriptional activation of ITGA6." (PMID 40198125, 2025). "To determine the role of HINT1 in VSMCs in the progression of aortic aneurysm, we constructed VSMC-specific Hint1-knockout (Hint1SMKO) mice by crossing Hint1fl/fl mice with Tagln-Cre mice." (PMID 40198125, 2025). "In the present work, we identified the role of HINT1 in VSMC phenotypic switching and the pathogenesis of aortic aneurysms." (PMID 40198125, 2025). "HINT1 promotes VSMC phenotypic switching and aortic aneurysm by targeting ITGA6/FAK axis." (PMID 40198125, 2025). "However, the roles of HINT1 in VSMCs and aortic aneurysm have not been addressed." (PMID 40198125, 2025).
Autosomal recessive axonal neuropathy with neuromyotonia (1 paper, 2021). "Indeed, a series of human HINT1 mutants cause autosomal recessive axonal neuropathy with neuromyotonia (ARAN-NM)." (PMID 34827679, 2021).
Bradykinesia (1 paper, 2026). Bradykinesia literally means slow movement, and is used clinically to denote a slowness in the execution of movement (in contrast to hypokinesia, which is used to refer to slowness in the initiation of movement). "In contrast, five out of six patients with HINT1 pathogenic variants exhibited a postural tremor, and one patient additionally showed bradykinesia." (PMID 41549766, 2026).
Brody disease (1 paper, 2021). "Other genes examined in these NDM patients were CAV3, ATP2A1 (Brody disease) and HINT1 (hereditary neuromyotonia with axonal neuropathy)." (PMID 33263785, 2021).
cognitive disorder (1 paper, 2018). A disease affects cognitive processes. "Therefore, we speculate that HINT1 may function as a general clock gene and thereby affect emotional and cognitive disorders induced by disrupted circadian rhythms." (PMID 29937721, 2018).
Cognitive impairment (1 paper, 2018). Abnormal cognition is characterized by deficits in thinking, reasoning, or remembering. "Based on these findings, we speculate that CL and darkness promote HINT1 expression in specific encephalic regions and may trigger apoptotic pathways, ultimately causing affective disorders and cognitive impairment." (PMID 29937721, 2018).
experimental autoimmune encephalomyelitis (1 paper, 2019). An autoimmune demyelinating disease of the central nervous system that is produced experimentally in animals by the injection of homogenized brain or spinal cord in Freund's adjuvant. "Previously we have shown that HINT1/Hsp70 treatment induced regulatory NK cells ameliorating experimental autoimmune encephalomyelitis (EAE) course and CD4+ T cells proliferation." (PMID 31362466, 2019).
glioma (1 paper, 2017). A benign or malignant brain and spinal cord tumor that arises from glial cells (astrocytes, oligodendrocytes, ependymal cells). "Of these 8 genes, 6 (SULT4A1, NDRG4, GAP43, BEX1, HINT1, LZTS1) are believed to act as tumor suppressants, while the remaining two, PKM and VIPR1, have been found to be overexpressed in glioma." (PMID 28957313, 2017).
heart failure (1 paper, 2022). Inability of the heart to pump blood at an adequate rate to meet tissue metabolic requirements. "It protects against the development of heart failure in pressure-overloaded hearts by inhibiting Hint1." (PMID 34791525, 2022). "Hint1 is a tumour suppressor that activates the ATM kinase and the DNA damage response (DDR), a process that is prominent in cardiomyocytes of patients with heart failure." (PMID 34791525, 2022).
Hyperglycemia (1 paper, 2023). An increased concentration of glucose in the blood. "Our findings indicate that CD31 density was lower in Hint1-KO mice than WT mice in both basal and STZ-induced hyperglycemia conditions." (PMID 38068718, 2023).
leukemia (1 paper, 2024). A malignant (clonal) hematologic disorder, involving hematopoietic stem cells and characterized by the presence of primitive or atypical myeloid or lymphoid cells in the bone marrow and the blood. "Furthermore, HINT1 overexpression re-sensitized SIRT5 knocked down leukemia cells to 6-MP in the presence of histidine." (PMID 38485947, 2024).
limb ischemia (1 paper, 2023). A ischemia that involves the limb. "Our findings expand our knowledge of the Hint1 function and highlight its novel role in protecting against limb ischemia by maintaining mitochondrial homeostasis." (PMID 38068718, 2023). "Further investigations are warranted to fully understand the underlying mechanisms and to explore the translational potential of Hint1 as a therapeutic target in the clinical management of limb ischemia." (PMID 38068718, 2023). "Further investigation revealed that Hint1 maintains mitochondrial homeostasis and energy metabolism in endothelial cells, contributing to its protective effect against limb ischemia." (PMID 38068718, 2023). "The significant impact of Hint1 on maintaining endothelial cell mitochondrial function highlights its potential as a promising therapeutic target for the treatment of limb ischemia." (PMID 38068718, 2023). "Moreover, the specific overexpression of Hint1 in endothelial cells using AAV9 was shown to enhance blood flow restoration and angiogenesis, indicating that Hint1 serves as a protective factor against limb ischemia." (PMID 38068718, 2023). "In the context of limb ischemia, our study delves into the intriguing role of Hint1." (PMID 38068718, 2023). "By targeting Hint1, interventions aimed at preserving or restoring mitochondrial function may hold great promise for improving outcomes in patients with limb ischemia." (PMID 38068718, 2023). "However, we found that endothelium-specific overexpression of Hint1 can enhance perfusion recovery after limb ischemia." (PMID 38068718, 2023). "However, the precise role of Hint1 in limb ischemia has remained unclear." (PMID 38068718, 2023). "To investigate the impact of Hint1 on limb ischemia, we administered AAV9 vectors carrying the Hint1 gene under the Tie2 promoter (AAV9-Tie2-Hint1-EGFP) through tail vein injection in mice." (PMID 38068718, 2023). "This study demonstrates that Hint1 plays a crucial protective role against limb ischemia in normal and hyperglycemic conditions." (PMID 38068718, 2023).
mental disorder (1 paper, 2017). A disease that has its basis in the disruption of mental process. "It is necessary to further investigate the mechanism of HINT1 associations with gender differences in mental disorders." (PMID 29075577, 2017).
myopia (1 paper, 2024). "Eight pairs (protein-coding genes TOM1L2, MXRA7, RHPN2, and HINT1 for senile cataract, WARS1 and TDRD7 for AMD, STAT6 for myopia, and TPPP3 for DR) are newly reported in this study." (PMID 39408566, 2024).
non-small cell lung carcinoma (1 paper, 2016). A group of at least three distinct histological types of lung cancer, including non-small cell squamous cell carcinoma, adenocarcinoma, and large cell carcinoma.
Pituitary Adenomas (1 paper, 2021). "This is a first report on Hint1 expression in pituitary adenomas." (PMID 33671384, 2021). "We found that Hint1 expression is higher in invasive pituitary adenomas, showing a possible relation with the expression of cell proliferation markers and angiogenic factors; it could also be related to invasive behavior." (PMID 33671384, 2021).
polyneuropathy (1 paper, 2026). A disease or disorder affecting more than one nerve. "Nerve conduction studies in patients with HINT1‐related polyneuropathy." (PMID 41549766, 2026).
prostate carcinoma (1 paper, 2013). A carcinoma that arises from epithelial cells of the prostate gland. "Fixed threshold (criteria >) values for putative biomarkers for diagnosis range between 0.68 and 0.74, indicating high sensitivity for NDRG1, BTF3 and HINT1, as diagnostic markers for identifying prostate cancer in tissue cores by unbiased, quantitative immunohistochemistry." (PMID 24386364, 2013). "It is tempting to speculate that HINT1 may contribute towards the inhibition of Wnt/ß-catenin signaling in prostate cancer." (PMID 24386364, 2013). "We then employed a quantitative immunofluorescence approach to stratify prostate cancer using co-localization coefficients of BTF3, HINT1 and NDRG1." (PMID 24386364, 2013). "We used quantitative immunohistochemistry to show that the expression of BTF3, HINT1, NDRG1 and ODC1 proteins is increased in prostate cancer tissue and could serve as putative targets for the investigation of carcinogenesis or biomarkers for disease." (PMID 24386364, 2013). "We chose four genes BTF3, NDRG1, HINT1 and ODC1 that are up-regulated in prostate carcinoma (oncomine.org; selection criteria: p=0.0001, 2 fold change and in top 10% of genes over-expressed in the overall dataset) in at least four normal vs cancer prostate gene expression analysis datasets." (PMID 24386364, 2013). "BTF3, HINT1, NDRG1 and ODC1 could be developed as epithelial specific biomarkers for tissue based diagnosis and stratification of prostate cancer." (PMID 24386364, 2013). "No information exists on HINT1 expression or function in prostate cancer although it may act as tumor suppressor in mice." (PMID 24386364, 2013). "Furthermore, BTF3, NDRG1 and HINT1, in quantitative co-localization studies appear capable of discriminating between biochemical relapse and non-relapse prostate cancer." (PMID 24386364, 2013).
rectal cancer (1 paper, 2022). A primary or metastatic malignant neoplasm that affects the rectum. "Specifically, our team found that Hint1 can inhibit the proliferation of rectal cancer cells by directly binding to Posh-JNK2 complexes, inhibiting the transcriptional activity of AP-1, which is an important cancer transcription factor." (PMID 35241097, 2022).
small cell carcinoma (1 paper, 2017). A neuroendocrine carcinoma composed of small malignant cells which are often said to resemble "oat cells" under the microscope. "Interestingly, AK1RC3 has been suggested as an adjunct marker for differentiating small cell carcinoma from NSCLC, and the increased expression of HINT1 inhibits the growth of NSCLC cell lines." (PMID 28768489, 2017).
status epilepticus (1 paper, 2016). Status epilepticus is defined as a continuous seizure lasting more than 30 min, or two or more seizures without full recovery of consciousness between any of them. "Similarly, NMDAR-induced continuous seizures (status epilepticus) can be controlled by CB1R and here, CBD and regulators of HINT1-σ1R activity seem to be promising agents." (PMID 27323834, 2016). "Therefore, it is feasible that continuous seizures (status epilepticus) can be controlled by acting on GPCRs like CB1R or 5HT1A receptors, with the HINT1-σ1R tandem coupling their function to that of over activated NMDARs." (PMID 27323834, 2016).